SLC20A2 (solute carrier family 20 member 2)
Description:
Sodium-phosphate symporter which preferentially transports the monovalent form of phosphate with a stoichiometry of two sodium ions per phosphate ion. Plays a critical role in the determination of bone quality and strength by providing phosphate for bone mineralization (By similarity). Required to maintain normal cerebrospinal fluid phosphate levels (By similarity). Mediates phosphate-induced calcification of vascular smooth muscle cells (VCMCs) and can functionally compensate for loss of SLC20A1 in VCMCs (By similarity). (Microbial infection) Functions as a retroviral receptor and confers human cells susceptibility to infection to amphotropic murine leukemia virus (A-MuLV), 10A1 murine leukemia virus (10A1 MLV) and some feline leukemia virus subgroup B (FeLV-B) variants.
Synonyms: GLVR-2; PiT-2; Pit2; GLVR2; Ram-1; IBGC1; IBGC2; IBGC3; MLVAR; RAM1
Tractability: Antibody: UniProt places it where antibodies can reach, with high confidence; its Gene Ontology location is reachable by antibodies, with high confidence; UniProt predicts a signal peptide or a membrane-spanning region. PROTAC: ubiquitination databases record sites on it; its protein half-life has been measured; a small molecule that binds it is known.
Target class: Electrochemical transporter; SLC20 family of sodium-dependent phosphate transporters; Transporter; SLC superfamily of solute carriers
Gene: Protein-coding gene on chromosome 8 (42,416,449 to 42,542,530, reverse strand). Ensembl gene ENSG00000168575.
Subcellular location: Cell membrane; Apical cell membrane
Pathways (Reactome):
Disease: Defective SLC20A2 causes idiopathic basal ganglia calcification 1 (IBGC1)
Transport of small molecules: Sodium-coupled phosphate cotransporters
Gene Ontology:
Molecular function: sodium:phosphate symporter activity; virus receptor activity; signaling receptor activity; phosphate transmembrane transporter activity
Biological process: phosphate ion transmembrane transport; positive regulation of bone mineralization; phosphate ion transport; sodium ion transmembrane transport; symbiont entry into host cell
Cellular component: extracellular exosome; plasma membrane; apical plasma membrane; brush border membrane; membrane
Genetic constraint (gnomAD): Loss-of-function variants: 24 observed, 52.44 expected, observed/expected ratio (o/e) 0.46, 90% interval 0.33 to 0.64. The upper end of that interval is the gene's LOEUF score, 0.64, which puts it in group 2 of 6, group 1 being the genes least tolerant of losing a copy. Missense variants: 570 observed, 829.5 expected, observed/expected ratio (o/e) 0.69, 90% interval 0.64 to 0.74. Synonymous variants: 324 observed, 343.4 expected, observed/expected ratio (o/e) 0.94, 90% interval 0.86 to 1.03.
Homologues: Orthologues: chimpanzee SLC20A2 (99% identical), macaque SLC20A2 (99% identical), guinea pig SLC20A2 (93% identical), rat Slc20a2 (92% identical), mouse Slc20a2 (92% identical), pig SLC20A2 (89% identical), dog SLC20A2 (88% identical), tropical clawed frog slc20a2 (82% identical), zebrafish slc20a2 (79% identical), rabbit SLC20A2 (78% identical), Drosophila melanogaster NaPi-III (42% identical), Caenorhabditis elegans pitr-1 (35% identical), and 4 more. Paralogues in human: SLC20A1 (62% identical).
Diseases named in the same sentence as SLC20A2 in open-access papers:
SLC20A2 is named in the same sentence as 71 diseases in open-access papers, as found by Europe PMC text mining. Sharing a sentence is not in itself a finding about the gene and the disease. The quoted sentences say what the papers report.
Fahr’s disease (18 papers, 2013 to 2025). "Both parents, who are first‐degree cousins, are heterozygous for a pathogenic variant in the SLC20A2 gene, associated with Fahr’s disease." (PMID 41458256, 2025). "Heterozygous mutations of SLC20A2 have been identified in primary familial brain calcification (PFBC), an inherited form of neurological disorders characterized by cognitive impairments." (PMID 38195526, 2024). "This case report describes an exceptionally rare case in which a prior diagnosis of schizophrenia was later determined to be early-onset Fahr’s disease, linked to a genetic mutation in the SLC20A2 gene." (PMID 38835553, 2024). "This article describes a case of familial Fahr disease most likely caused by a novel frameshift mutation in SLC20A2 (c.1097delG p.G366fs*89)." (PMID 36397039, 2022). "Several polymorphisms in SLC20A2 are responsible for most Primary Familial Brain Calcification cases, a heterogeneous neuropsychiatric disorder." (PMID 33101375, 2020). "Mutations in the SLC20A2-gene encoding the inorganic phosphate (Pi) transporter PiT2 can explain approximately 40 % of the familial cases of the rare neurodegenerative disorder primary familial brain calcification (Fahr’s disease)." (PMID 26660102, 2016). "Their targeted gene was SLC20A2 whose mutations cause the familial idiopathic basal ganglia calcification (Fahr’s disease) molecularly demonstrated as deposits of calcium in basal ganglia and other distinct brain regions." (PMID 25916600, 2015). "Notably, Zhang and colleagues discovered a novel SLC20A2 mutation in a Fahr’s disease-affected family and managed to secure dermal fibroblasts from a member of this family." (PMID 37629187, 2023). "Research has pointed toward various SLC20A2 mutations as potential culprits behind Fahr’s disease, which is a subset of primary familial brain calcification (PFBC)." (PMID 37629187, 2023). "Recent work has shown that primary familial brain calcification (PFBC), an inherited form of neurological disorder with a wide spectrum of cognitive aspects, is associated to mutations in SLC20A2, a sodium (Na)-Phosphate (Pi) co-transporter." (PMID 38195526, 2024). "Genes implicated in Fahr's disease include PDGFB, PDGFRB, SLC20A2, XPR1, MYORG, and JAM2." (PMID 37780723, 2023). "By contrast, identification of heterozygous pathogenic variants in SLC20A2 that cause autosomal dominantly‐inherited primary familial brain calcification (PFBC; idiopathic basal ganglia calcification [IBGC]) indicates a role for SLC20A2 in the regulation of tissue mineralization." (PMID 30721528, 2019). "Recent genetic research identified mutations in SLC20A2, a gene located in the IBGC3 region that encodes for type III sodium-dependent phosphate transporter 2 (PiT2) as a major cause for dominantly inherited Fahr’s disease." (PMID 26951767, 2016).
Basal ganglia calcification (10 papers, 2013 to 2025). The presence of calcium deposition affecting one or more structures of the basal ganglia. "Here, we first report a case of familial basal ganglia calcification potentially caused by a frameshift mutation in SLC20A2 (c.1097delG p.G366fs *89)." (PMID 36397039, 2022). "We herein describe a 64-year-old Japanese IBGC1 patient with bilateral basal ganglia calcification carrying a novel SLC20A2 variant (p.Val322Glufs*92)." (PMID 31645982, 2019). "Recently, SLC20A2 mutations have been found in patients with idiopathic basal ganglia calcification (IBGC), and were predicted to bring about an inability to transport Pi from the extracellular environment." (PMID 28720798, 2017).
Parkinsonism (9 papers, 2017 to 2026). Characteristic neurologic anomaly resulting from degeneration of dopamine-generating cells in the substantia nigra, a region of the midbrain, characterized clinically by shaking, rigidity, slowness of movement and difficulty with walking and gait. "Here, we report the case of a Chinese woman with PFBC due to a novel SLC20A2 variant, who presented with parkinsonism while responding well to dopaminergic therapy, exhibiting symptom fluctuations and levodopa-induced dyskinesia during progression." (PMID 39036637, 2024). "As the cooccurrence of SLC20A2-associated PFBC with dopamine-responsive parkinsonism is very unusual, monitoring the dopamine responsiveness of the patient to assess the possible benefits of dopamine replacement therapy is essential." (PMID 39036637, 2024). "Patients with SLC20A2 mutations are more susceptible to movement disorders, cognitive impairments, and psychiatric symptoms, especially parkinsonism and memory problems, compared with patients with PFBC caused by other gene mutations." (PMID 33889180, 2021). "Patients with SLC20A2 mutation have a comparably high incidence of movement disorders, such as parkinsonism, accounting for approximately 70% of patients." (PMID 33889180, 2021). "The most common neurological symptoms in patients with SLC20A2 mutation are movement disorders, such as parkinsonism, tremor, dystonia, and gait disturbance." (PMID 33889180, 2021). "Herein, we report an IBGC1 patient with a novel variant in SLC20A2 associated with dopa-responsive parkinsonism." (PMID 31645982, 2019). "Variants in SLC20A2 are the most common, with patients with PFBC with this allele having a higher probability of developing parkinsonism." (PMID 39036637, 2024). "A systematic review of FIBGC reported that headaches are more common in PDGFB (32.5% of cases), and parkinsonism is more common in SLC20A2 (21% of cases)." (PMID 36206226, 2022). "Dopamine transporter single photon emission computed tomography using 123I-ioflupane and 123I-metaiodobenzylguanidine cardiac scintigraphy revealed pre-synaptic dopaminergic deficit and cardiac sympathetic nerve dysfunction in two SLC20A2-related PFBC patients with parkinsonism." (PMID 28935882, 2017). "Significantly higher bladder sub-scores were found in MYORG patients (compared to SLC20A2 subjects and patients without known genetic variants, p = 0.009), as well as in subjects with parkinsonism and cognitive decline compared to asymptomatic subjects (p = 0.042)." (PMID 38999439, 2024).
calcification (8 papers, 2018 to 2025). Process by which organic tissue becomes hardened by the physiologic deposit of calcium salts. "c.806delC co-segregated with brain calcification and led to SLC20A2 haploinsufficiency among the affected family members." (PMID 34025715, 2021). "Keywords “primary familial brain calcification” and “SLC20A2” were most prominent." (PMID 40456615, 2025).
cognitive deficits (6 papers, 2019 to 2025). "Patients with SLC20A2 mutation-induced PFBC usually exhibit several cognitive impairments and psychiatric symptoms after 40 years of age." (PMID 33889180, 2021). "However, Slc20a2-HO mice only exhibited long-term spatial learning memory impairments and sensorimotor gating deficits, as revealed by MWM and PPI tests, which corresponded with cognitive impairments and psychiatric signs observed in patients with SLC20A2 mutation." (PMID 33889180, 2021). "This integrative analysis identifies SLC20A2 and MYORG as predominant genetic contributors to PFBC, with distinct neuropsychiatric manifestations (cognitive deficits, psychiatric symptoms) representing hallmark clinical features." (PMID 40456615, 2025). "SLC20A2 and MYORG variants had higher detection rates, with cognitive impairment and psychiatric symptoms being common in PFBC patients." (PMID 40456615, 2025). "One of the two children carrying the SLC20A2 mutation suffers from panic disorder and depression but has no movement disorder or cognitive deficits (29/30 points in the MMSE)." (PMID 37341843, 2023). "Therefore, the decreased neuronal branching phenotype observed after Slc20a2 downregulation could contribute, at least in part, the neuronal death, neuroinflammation and severe cognitive deficits." (PMID 38195526, 2024).
cognitive decline (2 papers, 2019 to 2024). "Recently, mutations in four different genes (SLC20A2, PDGFRB, PDGFB, and XPR1) were identified, together with novel mutations in the Myogenic Regulating Glycosylase gene, causing the occurrence of movement disorders, cognitive decline, and psychiatric symptoms." (PMID 31267306, 2019).
epilepsy (2 papers, 2019 to 2020). A brain disorder characterized by episodes of abnormally increased neuronal discharge resulting in transient episodes of sensory or motor neurological dysfunction, or psychic dysfunction. "Here we describe a family with a novel SLC20A2 mutation mainly presenting with neurological symptoms including cortical myoclonus and epilepsy." (PMID 32274582, 2020). "While epilepsy, although rare, has been reported in patients with IBGC associated with SLC20A2 mutations, cortical myoclonus seems to be a new manifestation." (PMID 32274582, 2020). "While epilepsy has been reported in seven cases with IBGC and SLC20A2 mutations, cortical myoclonus has not been reported to our knowledge." (PMID 32274582, 2020).
hyperphosphatemia (2 papers, 2022 to 2023). Abnormally high level of phosphate in the blood. "The second pathway is the impairment of brain Pi homeostasis, either by hyperphosphatemia or by disrupted transport of phosphate in the brain; these patients suffering from this pathway defects may have mutations in SLC20A2, XPR1, or GNAS gene and usually show significantly increased CSF Pi levels." (PMID 36443312, 2022).
preeclampsia (2 papers, 2020 to 2024). Preeclampsia is a hypertensive disorder of pregnancy that is characterized by new-onset hypertension with proteinuria presenting after 20 weeks of gestation, and depending on mild or severe forms may initially present with severe headache, visual disturbances, and hyperreflexia. "Similarly, reduced levels of SLC20A1 and SLC20A2 in human placentas have been linked to early-onset preeclampsia, indicating that disruptions in these proteins can affect immune regulation and angiogenesis." (PMID 39544937, 2024). "In early preeclampsia (PE), placental expression of the sodium-dependent phosphate transporters Slc20a1 and Slc20a2 is highly reduced; yet in late PE, Slc20a2 is significantly increased." (PMID 32722465, 2020).
Stroke (2 papers, 2025). Sudden impairment of blood flow to a part of the brain due to occlusion or rupture of an artery to the brain. "Of the 5 index patients with SLC20A2 variants, 2 (P3 and P5) had had vascular events—TIA at a young age in P3 and stroke at 67 years in P5—and both also had confluent WMH (grade 3)." (PMID 40947452, 2025).
Anxiety (1 paper, 2024). Intense feelings of nervousness, tension, or panic often arise in response to interpersonal stresses. "We demonstrate that although both Slc20a1 and Slc20a2 impact spatial and episodic memory, only Slc20a1 affects contextual memory, while only Slc20a2 is linked to anxiety-related phenotypes." (PMID 38195526, 2024). "Our results also showed that solely Slc20a2 downregulation impacted exploratory- and anxiety-like behaviors, as demonstrated by our results in the OFT and D/LT tests." (PMID 38195526, 2024). "Moreover, the induction of neuroinflammation and neuronal death in the HpC after Slc20a2 downregulation could also explain, at least in part, the exploratory- and anxiety-like behavioral phenotypes observed in these mice." (PMID 38195526, 2024).
bipolar disorder (1 paper, 2020). A disorder of the brain that causes unusual shifts in mood, energy, activity levels and the ability to carry out day-to-day tasks. "Mutations or deletion in SLC20A2 are associated with psychiatric conditions (56.9%) including bipolar disorder, mood disturbances and psychosis and neurological symptoms mainly affecting cognitive abilities (58.8%) and motor function (54.9%), including dystonia, chorea, parkinsonism and ataxia." (PMID 32274582, 2020).
cataract (1 paper, 2019). Partial or complete opacity of the crystalline lens of one or both eyes that decreases visual acuity and eventually results in blindness. "Ectopic brain calcification was accompanied by a markedly increased incidence of cataracts in Slc20a2–/– mice." (PMID 30721528, 2019).
papillary thyroid carcinoma (1 paper, 2020). "We found that cg00768487 (UBXN11) and cg03110787 (MLLT1) have been associated with papillary thyroid carcinoma, cg10806146 (SLC20A2) and cg15936066 (SLC20A2) with prostate cancer, cg15936066 (SLC20A2) with systemic lupus erythematosus, and cg07538190 (C8orf58) with psoriasis." (PMID 32493484, 2020).
pseudohypoparathyroidism (1 paper, 2024). "Despite the thorough analysis, no known pathogenic variants were found in genes typically associated with Fahr’s syndrome (e.g., XRP1, PDGFRB, JAM2, PDGFB, SLC20A2, or MYORG) or pseudohypoparathyroidism (e.g., GNAS, STX16, or GNASAS1)." (PMID 39519162, 2024).
retinitis (1 paper, 2023). Inflammation of the retina. "Pdgfbret/ret and Slc20a2-HO mice exhibited persistent retinitis and ocular degeneration, suggesting high-Pi-induced neuroinflammation." (PMID 36741925, 2023).
infection (13 papers, 2011 to 2024). The state of being infected such as from the introduction of a foreign agent such as serum, vaccine, antigenic substance or organism. "CHOK1 cells expressing SLC20A2, exposed to A-MLV-GFP and wild type A-MLV 4070 at one week post-infection, were challenged with A-MLV envelope vectors expressing βgal." (PMID 21729311, 2011). "A-MLV infection renders MDTF/SLC20A2-HA cells resistant to A-MLV/βgal but not GALV/βgal vectors." (PMID 21729311, 2011).
tumor (12 papers, 2012 to 2024). "Despite such discrepancies, we found two splice events from genes PPP3CA and SLC20A2 that are significantly up- and down-regulated in a tumor–specific fashion." (PMID 23181285, 2012).
movement disorder (4 papers, 2019 to 2023). Neurological conditions resulting in abnormal voluntary or involuntary movement, which may impact the speed, fluency, quality and ease of movement. "Patients with SLC20A2 mutation were more likely to be affected by movement disorders; however, they were barely seen in Slc20a2-HO mice, where the main functional regions for motor regulation were seldom calcified." (PMID 33889180, 2021). "Among symptomatic patients (44.8%), the most common symptoms were chronic headache (23.3%), movement disorders (20%), and vertigo (16.7%); moreover, total calcifications score was related to clinical symptoms and was higher in patients with SLC20A2 mutations." (PMID 31267306, 2019).
genetic disease (1 paper, 2016). "IBGC3 is a familial genetic disease defined by genetic mutations in the major causative gene (SLC20A2)." (PMID 27777849, 2016).
mitochondrial disease (1 paper, 2025). "Eight patients had IBGC (variants in SLC20A2, PDGFB, MYORG), 4 had mitochondrial disease (MT-TL1), and 2 had monogenic vascular conditions (GAL, MAP3K6)." (PMID 40947452, 2025).
SLC20A2 also shares sentences with these, for which no sentence is quoted: cancer (3 papers); developmental delay (2); Dystonia (2); memory impairment (2); neurodegenerative disease (2); neurological disease (2); osteosarcoma (2); Alzheimer disease (1); anemia (1); ankylosis (1); Areflexia (1); astrocytoma (1); chronic headaches (1); coagulation disorders (1); cognitive disorder (1); colorectal cancer (1); dentin dysplasia (1); depression (1); diabetes (1); endothelial dysfunction (1); focal epilepsy (1); frontal lobe epilepsy (1); fungal infection (1); gastric cancer (1); generalized epilepsy (1); glioblastoma (1); glioma (1); Headache (1); Hyperinsulinemia (1); hypophosphatemia (1).
A further 20 diseases each share a sentence with SLC20A2 in 1 paper.